SLC25A3 (solute carrier family 25 member 3)
Description:
Inorganic ion transporter that transports phosphate or copper ions across the mitochondrial inner membrane into the matrix compartment (By similarity). Mediates proton-coupled symport of phosphate ions necessary for mitochondrial oxidative phosphorylation of ADP to ATP (By similarity). Transports copper ions probably in the form of anionic copper(I) complexes to maintain mitochondrial matrix copper pool and to supply copper for cytochrome C oxidase complex assembly. May also play a role in regulation of the mitochondrial permeability transition pore (mPTP) (By similarity).
Synonyms: PTP; PHC; OK/SW-cl.48; PiC
Tractability: Antibody: its Gene Ontology location is reachable by antibodies, with high confidence; UniProt predicts a signal peptide or a membrane-spanning region. PROTAC: ubiquitination databases record sites on it; its protein half-life has been measured.
Target class: Electrochemical transporter; Transporter; SLC25 family of mitochondrial transporters; SLC superfamily of solute carriers
Gene: Protein-coding gene on chromosome 12 (98,592,455 to 98,606,379, forward strand). Ensembl gene ENSG00000075415.
Subcellular location: Mitochondrion inner membrane
Subcellular location (Human Protein Atlas): Mitochondria
Gene Ontology:
Molecular function: protein-containing complex binding; phosphate transmembrane transporter activity; phosphate:proton symporter activity
Biological process: phosphate ion transmembrane transport; mitochondrial phosphate ion transmembrane transport; proton transmembrane transport
Cellular component: extracellular exosome; membrane; mitochondrial inner membrane; mitochondrion; plasma membrane
Genetic constraint (gnomAD): Loss-of-function variants: 12 observed, 36.52 expected, observed/expected ratio (o/e) 0.33, 90% interval 0.21 to 0.53. The upper end of that interval is the gene's LOEUF score, 0.53, which puts it in group 2 of 6, group 1 being the genes least tolerant of losing a copy. Missense variants: 375 observed, 466.77 expected, observed/expected ratio (o/e) 0.8, 90% interval 0.74 to 0.88. Synonymous variants: 156 observed, 173.76 expected, observed/expected ratio (o/e) 0.9, 90% interval 0.79 to 1.02.
Gene-disease validity (ClinGen):
ClinGen rates the evidence that SLC25A3 causes each of these diseases.
mitochondrial disease (autosomal recessive): Moderate.
Homologues: Orthologues: chimpanzee SLC25A3 (96% identical), guinea pig SLC25A3 (93% identical), rabbit SLC25A3 (92% identical), macaque SLC25A3 (91% identical), pig SLC25A3 (91% identical), rat Slc25a3 (89% identical), mouse Slc25a3 (88% identical), tropical clawed frog slc25a3 (85% identical), zebrafish slc25a3b (81% identical), zebrafish slc25a3a (79% identical), Drosophila melanogaster Mpcp1 (69% identical), Drosophila melanogaster Mpcp2 (68% identical). Paralogues in human: SLC25A24 (22% identical), SLC25A20 (22% identical), SLC25A13 (20% identical), SLC25A25 (20% identical), SLC25A12 (20% identical), SLC25A22 (20% identical), SLC25A10 (20% identical), SLC25A18 (19% identical), SLC25A47 (19% identical), SLC25A37 (19% identical), SLC25A14 (18% identical), SLC25A21 (18% identical), and 37 more.
Diseases named in the same sentence as SLC25A3 in open-access papers:
SLC25A3 is named in the same sentence as 49 diseases in open-access papers, as found by Europe PMC text mining. Sharing a sentence is not in itself a finding about the gene and the disease. The quoted sentences say what the papers report.
cardiac hypertrophy (4 papers, 2013 to 2025). "On the other hand, long-term deletion of the SLC25A3 gene in the heart resulted in significant hypertrophy, with ventricular dilatation and reduced cardiac function, characteristics that are representative of the cardiomyopathy observed in humans with SLC25A3 mutations." (PMID 40141413, 2025). "Multiple studies clearly connect SLC25A3 to phosphate transport, and mutations in SLC25A3 lead to skeletal muscle myopathy and heart disease in humans and cardiac hypertrophy in mice." (PMID 33591272, 2021).
hypertrophic cardiomyopathy (4 papers, 2014 to 2025). A condition in which the myocardium is hypertrophied without an obvious cause. "Recessive variants in the SLC25A3-isoform A present with muscle hypotonia and hypertrophic cardiomyopathy." (PMID 33426505, 2020). "Mutations in SLC25A3 that encodes the phosphate carrier cause either hypertrophic cardiomyopathy and impaired function of other organs such as skeletal muscle or isolated cardiomyopathy." (PMID 30766870, 2019). "Notably, a homozygous mutation in SLC25A3 has been identified as cause of reduced mitochondrial ATP production in muscle, leading to mitochondrial phosphate carrier deficiency with lactic acidosis, hypertrophic cardiomyopathy and muscle hypotonia in humans." (PMID 41165044, 2025).
cardiomyopathy (3 papers, 2014 to 2025). A disease of the heart muscle or myocardium proper. "Furthermore, structural modifications in the protein have been described, and it has been recommended to consider SLC25A3 sequencing in patients with isolated cardiomyopathy, even in those without generalized skeletal myopathy or lactic acidosis." (PMID 40141413, 2025).
diabetes (3 papers, 2013 to 2023). "Another lncRNA that showed a strong correlation with FOXA2 and was downregulated in our study is SLC25A3, which its suppression has been reported to contribute to diabetes development by reducing ATP levels." (PMID 37670346, 2023).
depression (2 papers, 2018 to 2025). "Notably, when FDX1, LIPT1, and SLC25A3 are considered as potential drug targets, there is a concerning likelihood that they may precipitate an accelerated onset of colitis and depression." (PMID 40149491, 2025).
leukemia (2 papers, 2018 to 2021). A malignant (clonal) hematologic disorder, involving hematopoietic stem cells and characterized by the presence of primitive or atypical myeloid or lymphoid cells in the bone marrow and the blood. "Although considerable heterogeneity was present across groups, comparing protein expression profiles of the individual subunits that comprise CI-CV and SLC25A3 revealed that only 6 of the 110 subunits were similarly altered in leukemia." (PMID 34132194, 2021).
Mitochondrial phosphate carrier deficiency (2 papers, 2009 to 2023). "In our study, 11 oxidative stress-related genes were identified in the blue module.SLC25A3 encodes the mitochondrial phosphate carrier, whose mutation can lead to mitochondrial phosphate-carrier deficiency." (PMID 37814814, 2023).
osteosarcoma (2 papers, 2021 to 2022). A usually aggressive malignant bone-forming mesenchymal neoplasm, predominantly affecting adolescents and young adults. "Accumulating evidence indicates that homozygous mutations in SLC25A3 are correlated with generalized disorders in mitochondrial-energy metabolism and multisystemic clinical presentation; its high expression is associated negatively with the survival of patients with osteosarcoma." (PMID 35265521, 2022).
Skeletal myopathy (2 papers, 2025). "Mutations in SLC25A3, the gene encoding PiC, in humans lead to mitochondrial cardiomyopathy or skeletal myopathy." (PMID 40869261, 2025).
Alzheimer disease (1 paper, 2025). A progressive, neurodegenerative disease characterized by loss of function and death of nerve cells in several areas of the brain leading to loss of cognitive function such as memory and language. "Through this analysis, we identify three understudied proteins—Tagln2, Slc25a3, and Pafah1b3—that may contribute to the differential sensitivity of Wistar Han rats and C57BL/6 mice to STZ-icv and may play a role in the development and progression of Alzheimer’s disease." (PMID 40450637, 2025).
asthenozoospermia (1 paper, 2021). "In our study, bioinformatics analysis showed that proteins in the PPI network of ACO2, such as SLC25A3, are involved in energy metabolism and differentially expressed in patients with asthenozoospermia." (PMID 34213690, 2021).
atherosclerosis (1 paper, 2025). A disease characterized by the build-up of fatty material and calcium deposition in the arterial wall resulting in partial or complete occlusion of the arterial lumen. "Our findings identify mitochondrial Cu as a central mediator of D-flow-induced atherosclerosis and highlight the CTR1/SLC25A3 axis as a promising therapeutic target to mitigate mitochondrial dysfunction, cuproptosis, and atherosclerosis." (PMID 39975331, 2025). "This process involves SLC25A3 recruitment to plasma membrane caveolae/lipid rafts (C/LR), where it interacts with CTR1, leading to mitochondrial Cu overload, cuproptosis, and accelerated atherosclerosis." (PMID 39975331, 2025).
breast carcinoma (1 paper, 2013). "Within the tumor data sets, we observed more variability, with the highest CV being 42% for SLC25A3 in kidney cancer, and the highest MFC being 24 for SF3B2 in breast cancer." (PMID 24069164, 2013).
chronic apical periodontitis (1 paper, 2025). Chronic form of periapical periodontitis. "Importantly, immunohistochemical validation revealed spatial expression patterns of both NFE2L2 and SLC25A3 in apical periodontitis lesions." (PMID 40909264, 2025). "Among these, four CRGs were found to be down-regulated in chronic apical periodontitis (CAP), namely Nuclear Factor Erythroid 2-Related Factor 2 (NFE2L2), Dihydrolipoamide S-Succinyltransferase (DLST), Solute Carrier Family 25 Member (SLC25A3), and Glycine Cleavage H Protein (GCSH)." (PMID 40909264, 2025).
chronic myeloid leukemia (1 paper, 2022). "SLC25A3 transports phosphate into the mitochondrial matrix and is highly expressed in chronic myeloid leukemia." (PMID 35288533, 2022).
cognitive deficits (1 paper, 2025). "The ~ 20-fold higher expression of Slc25a3 in mice compared to rats, alongside its marked reduction in STZ-icv rats and AD patients, suggests that the greater Slc25a3 reserve in mice may contribute to their reduced susceptibility to STZ-icv-induced cognitive deficits." (PMID 40450637, 2025).
colon cancer (1 paper, 2022). "Typical immunohistochemical staining images obtained from The Human Protein Atlas of 9 DEMs (lacking SLC25A3) in colon cancer specimens and normal colon tissues are shown." (PMID 35288533, 2022).
colorectal cancer (1 paper, 2023). A primary or metastatic malignant neoplasm that affects the colon or rectum. "SLC25A3 is also differentially upregulated in UC and plays a potential carcinogenic role in UC-associated colorectal cancer." (PMID 37814814, 2023).
COVID-19 (1 paper, 2021). A disease caused by infection with severe acute respiratory syndrome coronavirus 2. "After comparing the collected genes, 460 host factors common to COVID-19 and dengue were found, including MMP2, PDF, PFKP, SLC25A3, IGF1, CCL4, TLR4, and AhR, and further analysis of interaction networks was performed." (PMID 34394108, 2021).
neuroblastoma (1 paper, 2010). Neuroblastoma (NB) is the most common solid, extracranial childhood tumor. "Notably, we compared the presence of the specific cassette exons in RNA from normal brain and neuroblastoma (for ATP6v0A1, STRADA, PCNP and CS) and from skeletal muscle and rhabdomyosarcoma (for TPM3, TPD52L2, NAP1L1, METT10 D and SLC25A3)." (PMID 20813049, 2010).
osteoporosis (1 paper, 2025). A condition of reduced bone mass, with decreased cortical thickness and a decrease in the number and size of the trabeculae of cancellous bone (but normal chemical composition), resulting in increased fracture incidence. "It showed that in osteoporosis patients, CP (P < 0.01), LIPT1 (P < 0.05), SLC25A3 (P < 0.001), and UBE2D3 (P < 0.01) were upregulated, while the expression levels of CDKN2A (P < 0.05), DBH (P < 0.01), DLST (P < 0.05), LOXL2 (P < 0.05), SLC31A1 (P < 0.05), and UBE2D1 (P < 0.01) were downregulated." (PMID 40980812, 2025).
Peptic ulcer (1 paper, 2025). The term peptic ulcer refers to acid peptic injury of the digestive tract, resulting in mucosal break reaching the submucosa. "SLC25A3: schizophrenia and peptic ulcer (excluding esophageal)." (PMID 40149491, 2025).
type I diabetes (1 paper, 2022). "During type I diabetes, miR-141 negatively regulates the solute carrier family 25 member 3 (Slc25a3), which is important for the transportation of an inorganic phosphate into the mitochondrial matrix for ATP synthesis." (PMID 36613495, 2022).
tumor (4 papers, 2013 to 2025). "Finally, these genes were overlapped with the upregulated DEGs from the two GSE9782 datasets, resulting in 7 tumor stemness-related genes, including NONO, CBX3, SLC25A3, PTPRG, NPM1, HINT1, HNRNPA1." (PMID 41050668, 2025). "However, the IHC results of SLC25A3 protein between normal and HCC tumor tissues were not existed in HPA, besides the obvious trend differences of ATP7A and ATP6AP1 expression in HCC patients were difficult to show in the HPA database." (PMID 36313717, 2022).
cancer (3 papers, 2022 to 2025). A tumor composed of atypical neoplastic, often pleomorphic cells that invade other tissues. "SLC25A3 and SLC25A37 encode two critical mitochondrial copper transporters, which potentially regulate cuproptosis in cancers." (PMID 36276096, 2022).
infection (3 papers, 2014 to 2023). The state of being infected such as from the introduction of a foreign agent such as serum, vaccine, antigenic substance or organism. "In addition, SLC25A3 also seems to represent a relatively common mitochondrial protein which responses to infection of various pathogens, including cytome-galovirus (CMV), transmissible gastroenteritis virus (TGEV)." (PMID 38029102, 2023).
myopathy (1 paper, 2020). A disease of the muscle in which the muscle fibers do not function properly. "Mutations in human SLC25A3/PIC cause a severe myopathy affecting skeletal and cardiac muscle in humans and in mice." (PMID 32080237, 2020).
SLC25A3 also shares sentences with these, for which no sentence is quoted: cardiac diseases (3 papers); cardiovascular disorder (1); colitis (1); dengue (1); Desminopathy (1); diarrheal disease (1); dilatation (1); hyperphosphatemia (1); Hypertension (1); hyperthyroidism (1); hypertrophy (1); hypothyroidism (1); kidney cancer (1); lactic acidosis (1); lung carcinoma (1); melanoma (1); neurodegenerative disease (1); Obesity (1); rhabdomyosarcoma (1); schizophrenia (1); skin cutaneous melanoma (1); tuberculosis (1).